EDN1 (endothelin 1)
Diseases named in the same sentence as EDN1 in open-access papers (continued):
Sharing a sentence is not in itself a finding about the gene and the disease.
endothelial dysfunction (continued). "Podocyte-derived EDN1 can act on endothelial cells, which mediates oxidative stress and endothelial dysfunction via EDN1 receptor type A (EDNRA) activation, thus promoting podocyte apoptosis." (PMID 32733268, 2020). "Endothelial dysfunction is characterized by an impairment of pulmonary vessel dilation, particularly mediated by overexpression of endothelin 1 (ET1) and suppression of the nitric oxide (NO)/NO-synthase (NOS) pathway." (PMID 32040829, 2020). "In the endothelial cells, IR causes an imbalance between the production of eNO and the secretion of endothelin-1, resulting in endothelial dysfunction." (PMID 33019649, 2020). "Endothelial dysfunction is reflected by biomarkers such as endothelin 1, homocysteine, and IL-6 (a proinflammatory cytokine)." (PMID 32695828, 2020). "Endothelin-1-mediated activation of the G protein-coupled endothelin A (ETA) receptor on vascular smooth muscle cells induces endothelial dysfunction, inflammation, and vasoproliferative effects." (PMID 31972008, 2020). "There was an inverse association between choroidal thickness and circulating markers of endothelial dysfunction (endothelin-1 r = −0.49, p ≤ 0.001; von Willebrand factor r = −0.32, p ≤ 0.05)." (PMID 33080821, 2020). "A component of green tea, (+)-catechin, has been proven to mitigate endothelial dysfunction, as reflected by diminished endothelin 1 levels, beside exerting antifibrosing and antioxidant activity." (PMID 32695828, 2020). "Endothelin-1 (ET-1) is a key inflammatory mediator in abnormal vascular tone, vascular remodeling, and especially endothelial dysfunction." (PMID 31293143, 2019). "Following endothelial dysfunction factors: endothelin 1 (Biomedica), MCP-1 (Bender Medsystems), sVCAM-1 (Biosource), ADMA (Immunodiagnost), homocysteine (Ahis-Shield), and PAI-1 (Technoclone) were determined by ELISAs method also." (PMID 31196144, 2019). "Endothelin-1 has important interactions with NO and is involved in the development of endothelial dysfunction." (PMID 31553765, 2019). "Impaired insulin signaling in BECs diminishes AKT-dependent NO production and simultaneously increases Endothelin 1 (ET-1) activity, which leads to endothelial dysfunction." (PMID 31798464, 2019). "Endothelial dysfunction characterized by increased endothelin-1 and decreased nitric oxide is also observed." (PMID 30999680, 2019). "In our study, the level of LDL was positively correlated with the markers of endothelial dysfunction, nitrites (r = 0.32) and endothelin-1 (r = 0.35) (p < 0.05)." (PMID 30871567, 2019). "Endothelial dysfunction is characterized by an imbalance between endothelial-derived vasodilating and vasoconstricting factors which are nitric oxide (NO) and endothelin-1 (ET-1), respectively, by which the former is downregulated and vice versa." (PMID 31485247, 2019). "Insulin resistance and secondary hyperinsulinaemia amplify endothelial dysfunction, mainly through the imbalance in the bioavailability of the vasodilator substances, such as nitric-oxide, and vasoconstrictor substances, such as endothelin-1." (PMID 31885899, 2019). "In the case of acromegaly, plasma levels of two biomarkers of endothelial dysfunction and atherosclerosis, such as endothelin-1 (ET-1) and total homocysteine levels (tHcy), were measured in patients with active acromegaly and cured disease." (PMID 29346331, 2018). "We examined the ability of metformin + esomeprazole to rescue TNF-α induced vascular cell adhesion molecule-1 (VCAM-1) and Endothelin-1 (ET-1) expression, leukocyte adhesion (markers of endothelial dysfunction)." (PMID 29466360, 2018). "Elevated plasma levels of endothelin-1 have been reported in T2D patients, thus suggesting that they contribute to endothelial dysfunction in these patients." (PMID 29707151, 2018). "Endothelin-1 (ET-1) plays important roles in endothelial dysfunction, vascular physiology, inflammation, and atherosclerosis." (PMID 29654172, 2018).
endothelial dysfunction (continued). "Endothelial dysfunction results in nitric oxide depletion and elevated endothelin-1, thus impairing the ability of arterioles to dilate while promoting vasoconstriction." (PMID 28542469, 2017). "Endothelin-1, derived mainly from endothelial cells, is a potent vasoconstrictor and marker of endothelial dysfunction." (PMID 28542479, 2017). "Endothelin-1 is also a marker of endothelial dysfunction and potent vasoconstrictor, which is produced by vascular endothelial cells." (PMID 28344817, 2017). "Endothelin-1 (ET-1) is mainly related to endothelial dysfunction, but other cells are also capable of producing the ET-1, such as vascular smooth muscle cells and mesangial cells of the kidney." (PMID 29267497, 2017). "FRG ameliorated endothelial dysfunction by downregulation of endothelin-1 (ET-1) and adhesion molecules in the aorta." (PMID 27322312, 2016). "Angiotensin II (Ang II) is a potent proinflammatory, prooxidant, and prothrombotic agent that favors endothelial dysfunction by increasing catecholamines, endothelin-1 (ET-1), and thromboxane A2 which increase blood pressure." (PMID 27293881, 2016). "The second marker was endothelin-1 (ET-1), a potent vasoactive peptide synthesized and released by the vascular endothelium, and plays an important role in vascular remodeling and endothelial dysfunction." (PMID 27579327, 2016). "Hypertriglyceridemia also stimulates the release and/or expression of endothelial mediators in vitro, such as endothelin-1, which significantly promotes endothelial dysfunction, a critical early step in the development of arteriosclerosis." (PMID 27192979, 2016). "A substantial amount of studies reveal that vascular inflammation contributes to endothelial dysfunction, which is reflected as decreased nitric oxide (NO) generation and increased endothelin-1 (ET-1) production." (PMID 26801405, 2016). "In patients with DN, inflammation leads to endothelial dysfunction, increased circulating levels of endothelin-1 (ET-1)." (PMID 27212945, 2016). "Endothelial dysfunction occurs due to decreased nitric oxide bioavailability and an increased level of endothelin-1 (ET-1), angiotensin II and oxidants, which contribute to a disequilibrium in endothelium-derived relaxing and contracting factors." (PMID 28536613, 2016). "Aside from impaired vascular expansion, the most important effects of endothelial dysfunction are those concerned with two substances produced by the endothelium: NO and endothelin-1 (ET-1)." (PMID 25949771, 2015). "Endothelial dysfunction is a precursor vascular disease usually elicited by the release of a variety of paracrine factors such as endothelin-1 that interact with platelets, inflammatory cells, and the vessel wall." (PMID 26823980, 2015). "Previously, on the same populations, we found that arsenic exposure increased endothelial dysfunction that was determined by plasma big-endothelin-1 (Big ET-1) concentrations." (PMID 26637202, 2015). "BC suppressed endothelial dysfunction by inducing downregulation of endothelin-1 and adhesion molecules in the aorta." (PMID 26504474, 2015). "Endothelial dysfunction is a significant imbalance of blood-vessel regulating substances produced by the vascular endothelium, such as nitric oxide (NO) and endothelin-1 (ET-1)." (PMID 25933220, 2015). "As result of an imbalance in vasodilating and vasoconstrictive factors such as nitric oxide (NO), endothelin-1 (ET-1) and urotensin-II (UT-II), endothelial dysfunction can lead to the development of hypertension via multiple mechanisms." (PMID 26580647, 2015). "Systemic inflammation and endothelial dysfunction with high production of endothelin-1 (ET-1) are also of importance." (PMID 25161617, 2014). "EGB ameliorated endothelial dysfunction by downregulation of endothelin-1 (ET-1) and adhesion molecules in the aorta." (PMID 24719637, 2014).
endothelial dysfunction (continued). "Endothelial dysfunction is a key feature of exposure to particulate matter (PM) and decreased endothelin-1 bioavailability is likely useful for brain function in the context of air pollution." (PMID 23986703, 2013). "High glucose-induced endothelial dysfunction is partially mediated by the down-stream pathophysiological effects triggered by increased expression of endothelin-1 (ET-1)." (PMID 24376792, 2013). "Endothelin-1 is a marker of endothelial dysfunction and it has been shown to be involved in a spectrum of cardiovascular diseases ranging from coronary artery disease to PH." (PMID 24312667, 2013). "Hypertrophy and excessive proliferation of endothelial cells (EC) contributes to increased intimal thickening and endothelial dysfunction, leading to an increase in vasoconstrictor molecules, such as endothelin-1 (ET-1)." (PMID 23739951, 2013). "Among suggested pathways leading to possible vasodilatory efficacy of statins, the restoration of endothelial dysfunction, increased nitric oxide synthesis with enhancement of eNOS mRNA stabilization or decreased synthesis of endothelin-1 (ET-1) are mentioned." (PMID 22645493, 2012). "Endothelin-1-induced oxidative stress promotes inflammatory responses and in turn contributes to the vascular remodeling and endothelial dysfunction in animal models of hypertension that present an endothelin-mediated component." (PMID 21915370, 2011). "Ghrelin administration acutely improves endothelial dysfunction by increasing nitric oxide bioavailability and normalizes the altered balance between endothelin-1 and nitric oxide within the vasculature of patients with metabolic syndrome." (PMID 20798901, 2010). "Gene expression of MMP-2 and MMP-9 in peripheral blood leukocytes and circulating levels of MMP-2, MMP-9, pro-inflammatory cytokines (TNF-α, IL-6), and endothelial dysfunction markers (Endothelin-1 [ET-1], adhesion molecules) were quantified via qRT-PCR and ELISA." (PMID 41598609, 2026). "Functional studies revealed that MALAT1 depletion increased, while MALAT1 overexpression decreased, the endothelial dysfunction markers endothelin-1 (ET-1) and vascular cell adhesion molecule-1 (VCAM1), indicating a protective role of MALAT1 in maintaining endothelial homeostasis." (PMID 41597229, 2026). "The vascular endothelium contributes to blood pressure by regulating vascular tone, and endothelial dysfunction is characterised by an increase in vasoconstrictors acting on the endothelial cells (i.e. endothelin‐1 (ET‐1)) and a reduction in the bioavailability of vasodilators (i.e. NO)." (PMID 40321041, 2025). "Finally, the neuropeptide theory indicates that the release of potent vasoconstrictors, such as endothelin-1 and thromboxane A2, can lead to severe cerebral vasoconstriction, followed by endothelial dysfunction and hypoperfusion." (PMID 41204247, 2025). "In contrast, with advancing age, the vascular response decreases, likely due to endothelial dysfunction involving endothelin-1 (ET1), a factor influenced by conditions such as hypertension, atherosclerosis, and chronic kidney disease, which contribute to vascular rigidity and a “spasmogenic” state." (PMID 40217865, 2025). "Additionally, insulin resistance can disrupt Phosphoinositide 3-kinase-dependent signaling, upsetting the balance between nitric oxide production and endothelin-1, ultimately leading to endothelial dysfunction." (PMID 39941621, 2025). "TMAO has been additionally characterized as a precursor of endothelial dysfunction by reducing the expression of endothelial nitric oxide synthase (eNOS), decreasing nitric oxide (NO) production, and increasing levels of endothelin-1 (ET-1)." (PMID 40219037, 2025). "For example, silencing of endothelial vWF has been shown to reduce angiotensin II–induced endothelin‐1 expression, suggesting that a LEF1‐vWF‐ET‐1 axis might contribute to endothelial dysfunction in AAA." (PMID 41208012, 2025).
endothelial dysfunction (continued). "Endothelial dysfunction results in increased vascular tone, thrombosis, and vascular permeability, and oxidative stress causes increased endothelin-1 activity that is not counterbalanced by NO." (PMID 39500819, 2025). "Furthermore, the ongoing inflammatory milieu induces endothelial dysfunction, reducing the production of vasodilatory nitric oxide (NO) and increasing the release of endothelin-1 (ET-1), promoting vasoconstriction and hypertension." (PMID 40969606, 2025). "In COPD and ILD, vascular remodeling is known to be caused not only by alveolar hypoxia but also by factors contributing to endothelial dysfunction, such as increased endothelin-1, decreased prostacyclin and nitric oxide, increased oxidative stress, inflammation, and genetic predisposition." (PMID 39859549, 2025). "This is due to VEGF and PlGF binding to circulating sFlt-1 instead of the target receptor, resulting in vasoconstriction and endothelial dysfunction, including increased secretion of endothelin-1, a vasoconstrictor, and a reduction in the generation of endothelial nitric oxide, a potent vasodilator." (PMID 40894072, 2025). "Endothelial dysfunction is a consequence of increased oxidative stress, reduced NO production, increased secretion of adipokines, endothelin-1, and fibroblast growth factor 2 (FGF-2), which stimulate inflammatory pathways, intimal growth, angiogenesis, and proliferation of smooth muscle cells." (PMID 38474219, 2024). "Additionally, individuals with CSF display endothelial dysfunction, as determined by biomarker assessment, namely endothelin-1 and nitric oxide concentrations or plasma levels of asymmetric dimethylarginine." (PMID 38279297, 2024). "High levels of leptin may induce the synthesis of endothelin-1 which leads to endothelial dysfunction." (PMID 37872379, 2024). "The main pathogenetic mechanisms in SSc-PAH are thought to be endothelial dysfunction and impaired balance between vasoconstrictor and vasodilator mediators such as endothelin-1 (ET-1), nitric oxide (NO), prostacyclin (PG-I2), and smooth muscle proliferation leading to vasculopathy." (PMID 38378970, 2024). "In the vasculature, the first sign of vascular abnormalities could be endothelial dysfunction, which results in elevated serum endocan and endothelin-1 levels." (PMID 39408883, 2024). "The proposed mechanisms for coronary vasospasm in vasculitis are endothelial dysfunction and vascular smooth muscle cells dysfunction, secondary to imbalance between vasodilators (nitric oxide and prostacyclin) and vasoconstrictors (endothelin-1 and angiotensin II)." (PMID 39682532, 2024). "Endothelial dysfunction leads to decreased production of vasodilators such as nitric oxide (NO) and prostacyclin and increased production of vasoconstrictors such as endothelin-1 (ET-1)." (PMID 39483752, 2024). "In patients with IR, the pathway-specific impairment of phosphatidylinositol 3-kinase–dependent signaling may result in an imbalance between the production of nitric oxide and the secretion of endothelin-1, which leads to endothelial dysfunction." (PMID 37255931, 2023). "Moreover, L-NAME increases EDN1 expression by stimulating ROS, which induces endothelial dysfunction and hypertension." (PMID 37214130, 2023). "The mechanisms underlying this phenomenon include hypertension with initial hyperperfusion and subsequent endothelial dysfunction, resulting in the expression of endothelin-1 and angiotensin II, ultimately leading to the remodeling of vascular anatomy with hypertrophy and fibrosis." (PMID 37629249, 2023). "Furthermore, the administration of quercetin significantly reduced blood pressure (BP) and improved endothelial dysfunction in hypertensive rats by inhibiting the endothelin-1 (ET-1)-induced enhancement of protein kinase C (PKC) activity." (PMID 37513932, 2023).
endothelial dysfunction (continued). "Thus, the aim of this review is to give an overview of current blood-based cardiac biomarkers and discuss the potential of endothelin-1 (ET-1) and more stable peptide fragments of ET-1 synthesis as biomarkers of endothelial dysfunction." (PMID 39802623, 2023). "In response to SARS-CoV-2 infection, EDN1 may be upregulated, leading to increased vascular tone and inflammation and subsequent endothelial dysfunction." (PMID 37239234, 2023). "Endothelial dysfunction is the imbalance of vasoconstrictors (such as prostaglandins, angiotensin II, and endothelin-1) and vasodilators (such as prostaglandins, NO, and endothelial-derived hyperpolarizing factors that can lead to vasoconstriction and vascular inflammation)." (PMID 36136468, 2022). "Both drugs could mitigate expression of the endothelial dysfunction markers, vascular cell adhesion molecule-1 and endothelin-1 (via qPCR)." (PMID 36076929, 2022). "Endothelin-1 (ET-1), one of the parameters of endothelial dysfunction, was measured." (PMID 35585936, 2022). "Furthermore, we focused on the inner mechanism of the interaction between losartan and axitinib-related endothelial dysfunction by measuring the levels of endothelin-1 and eNOs in rat serum." (PMID 35566115, 2022). "EDN1 induces vascular hypertrophy and endothelial dysfunction." (PMID 35205232, 2022). "Endothelial dysfunction results in decreased production of nitric oxide with increased vascular tone and microvascular resistance due to increased activity of vasoactive substances such as endothelin-1." (PMID 36178560, 2022). "Endothelin 1 (ET-1) served as a marker of endothelial dysfunction." (PMID 35563797, 2022). "Finally, there are changes in the production of vasoactive molecules, namely nitric oxide (NO), prostacyclins and endothelin-1 (ET-1), contributing to endothelial dysfunction and vasoconstriction." (PMID 35911521, 2022). "Endothelial dysfunction is characterized by impaired vasodilation, due to a reduction in NO and/or an increase in vasoconstricting factors such as endothelin 1 (ET‐1), which can decrease blood flow to subsequently limit oxygen transport and nutrient supply to skeletal muscle." (PMID 33225593, 2021). "Additionally, oxidative stress leads to increased endothelial-derived constricting factors such as endothelin-1 (ET-1), angiotensin II, thromboxane A2 and prostaglandin H2, thus enhancing vasoconstriction and contributing to endothelial dysfunction." (PMID 34206404, 2021). "Chronic inflammation in T2DM causes endothelial dysfunction, evident from the reduction of flow-mediated dilatation (FMD), makeing an imbalance between endogenous vasodilators such as NO and vasoconstrictors such as endothelin-1 (ET-1)." (PMID 34567218, 2021). "Additionally, sVCAM-1, sE-selectin, and endothelin-1 levels—considered as markers of endothelial dysfunction were reduced." (PMID 34578932, 2021). "Endothelial dysfunction arises from an imbalance in vasodilatory agents such as nitric oxide, prostacyclin and endothelial-derived hyperpolarising factors and vasoconstricting agents including angiotensin-II, prostaglandin and endothelin-1." (PMID 33499382, 2021). "Endothelial dysfunction is usually related to the imbalance of many factors, including a reduction in nitric oxide (NO) and production of endothelin-1 (ET-1) and thromboxane A2 (TXA2), which exhibit the features of pro-inflammation, pro-oxidation, pro-coagulation and pro-vascular adhesion." (PMID 34500559, 2021). "Overactivation of the endothelin-1 (ET-1) system contributes to endothelial dysfunction." (PMID 34926535, 2021). "Moreover, SFN suppresses endothelial inflammation by preventing TNF-α-mediated secretion of VCAM-1, ICAM-1, E-selectin, Endothelin-1 as well as hyperglycemia-induced endothelial dysfunction." (PMID 33988232, 2021).